APOB (apolipoprotein B)
Diseases named in the same sentence as APOB in open-access papers (continued):
Sharing a sentence is not in itself a finding about the gene and the disease.
hyperlipidemia (continued). "The serum apoM concentration in the PNS without hyperlipidemia group also positively correlated with HDL-C, LDL-C, apoA1, and apoB (r = 0.458, P = 0.003; r = 0.423, P = 0.017; r = 0.254, P = 0.022; and r = 0.427, P = 0.036, respectively)." (PMID 28877724, 2017). "The T2DM with hyperlipidaemia group had higher CYS-C, TC, TG, and apoB levels and lower FPG and HDL-C levels compared with the T2DM without hyperlipidaemia group." (PMID 27633510, 2016). "Hyperlipidemia was characterized by reduced circulating ILC3s, integrin α4+ ILC3s, and plasma IL-22, all of which showed inverse correlations with TC, TG, LDL-C, non-HDL-C, and ApoB." (PMID 41415268, 2025).
hypertriglyceridemia (145 papers, 2006 to 2026). A laboratory test result indicating elevated triglyceride concentration in the blood. "In the context of severe hypertriglyceridemia, partial loss-of-function APOB variants can paradoxically increase hepatic triglyceride accumulation by impairing VLDL export, thereby promoting steatosis despite lower plasma cholesterol concentrations." (PMID 41300829, 2025). "Other studies are consistent with these results and show that the biomarkers of hyperglycemia, hypertriglyceridemia, higher ApoA-I, and ApoB–to–ApoA-I ratio are significantly associated with T1DM risk." (PMID 38534969, 2024). "We measured the kinetics of LDL-apoB in plasma to explore the underlying metabolic mechanisms associated with reported hypertriglyceridemia and changes of apoB particle number in ACCi-treated patients." (PMID 36737040, 2023). "A GWA study of individuals with hypertriglyceridemia has shown that common variants in 4 genetic loci (APOB, LPL, GCKR, and APOA5) are significantly related to increased TG levels." (PMID 35999587, 2022). "Excessive ApoC3 can postpone the lipolysis of ApoB lipoprotein and inhibit its uptake by the normal high-affinity receptors of ApoB lipoprotein on hepatocytes, causing hypertriglyceridemia." (PMID 35453604, 2022). "The 2018 ACC/AHA cholesterol guideline mentions that ApoB levels may be useful in identifying whether hypertriglyceridemia is associated with increased atherosclerotic risk." (PMID 35342890, 2022). "In summary, adipocyte removal of triglycerides is independently associated with an atherogenic hypertriglyceridemia/hyperapoB profile in 2 independent populations and explains as much as 20% of the variation in the circulating levels of apoB and triglycerides between subjects." (PMID 23316323, 2012). "In contrast, polygenic hypertriglyceridemia and carriers of APOC3 or APOB variants exhibited a markedly higher prevalence of MASLD (65–70%)." (PMID 41300829, 2025). "Laboratory findings include severe hypertriglyceridemia, sometimes >1000 mg/dl, the milky appearance of fresh plasma, low apolipoprotein B levels, and low levels of post-heparin-plasma LPL activity." (PMID 41180755, 2025). "Quantitative alterations are well known and are characteristic of diabetic dyslipidemia, such as hypertriglyceridemia, hyper-apoB, and low levels of HDL." (PMID 39941533, 2025). "When recommended by guidelines and consensus groups, measurement of apoB has been prioritized or restricted to patients with hypertriglyceridaemia, the presumption being cholesterol-depleted apoB particles are only common in such individuals." (PMID 41127096, 2025). "Specifically, in healthy subjects, ApoC‐III is mostly found in ApoA‐carrying lipoproteins (i.e. HDLs), whereas in patients with hypertriglyceridemia, it is mostly found in ApoB‐carrying lipoproteins (i.e. LDLs or VLDLs)." (PMID 39822152, 2025). "Approximately 20% of individuals with metabolic disorders, including hypertriglyceridemia, type 2 diabetes, and obesity, exhibit discordance between apoB and LDL-C levels, underscoring the limitations of LDL-C-based risk assessment." (PMID 40852379, 2025). "In contrast, apoB is typically elevated in patients with moderate hypertriglyceridemia, because of the increased number of small dense LDL particles in these patients due to CETP-mediated lipid exchange and the subsequent increased lipolysis of LDL." (PMID 38331834, 2024). "Noteworthy alterations in free fatty acid levels, apoB decomposition, hypertriglyceridemia, and HDL levels also occurred Metformin treatment effectively mitigated total cholesterol, LDL, and triglyceride levels." (PMID 39585487, 2024). "Confirming our previous findings in a similar cohort, plasma apoB was associated positively with measures of GIISIVGTT, IR, plasma IL-1Ra, postprandial hypertriglyceridemia and hyperchylomicronemia." (PMID 37914804, 2023).
hypertriglyceridemia (continued). "The fourth research direction is a hot research area in recent years (green cluster) and includes hypertriglyceridemia, ApoB, LP(a), omega-3 fatty acids, icosapent ethyl, PCSK9 inhibitors, EPA, DHA." (PMID 38017531, 2023). "There is considerable evidence that ASCVD risk is higher in those with hypertriglyceridemia and high apoB versus those with hypertriglyceridemia and normal apoB levels." (PMID 35342890, 2022). "As standard plasma TG concentration assessment does not offer any information regarding the levels or the structure of TG-rich lipoproteins, apolipoprotein B (apoB) measurement has emerged as a novel representative of hypertriglyceridemia." (PMID 34067469, 2021). "It has been previously documented that overproduction of hepatic TG-rich VLDL and decreased degradation of apolipoprotein B (apoB), a major component of VLDL, in insulin-deficient and/or resistant individuals contribute significantly to hypertriglyceridaemia." (PMID 34365977, 2021). "The consequence consists of increased secretion of apolipoprotein B (apoB) and increased hepatic lipase activity, leading to hypertriglyceridemia." (PMID 33348926, 2020). "A statistically significant difference was detected in transgenic compared to wild-type animals at every time point (7, 9, and 12-month, n = 5 animals/group) indicating chronic hypertriglyceridemia in APOB-100 transgenic mice." (PMID 30410436, 2018). "Although the CV risk implications of hypertriglyceridemia and low HDL-C remain controversial, the CV significance of LDL-C and its main lipoprotein (apolipoprotein B (apoB)) is well established." (PMID 30671483, 2018). "HFD-induced hypertriglyceridemia was significantly improved in the mice that received 0.25% and 0.5% AI; the plasma levels of both TG and total apolipoprotein B (ApoB), the components of VLDL, were reduced." (PMID 28805698, 2017). "This suggests that postprandial chylomicron particles have an important role to play in postprandial hypertriglyceridaemia, together with insulin sensitivity and apoB." (PMID 26989412, 2016). "This suggests that postprandial chylomicron particles probably play an important role in contributing towards postprandial hypertriglyceridaemia, together with apoB and insulin sensitivity." (PMID 26989412, 2016). "In this "systemic steatosis" model, increased uptake of fatty acids in the liver promotes the synthesis of triglycerides and apolipoprotein B, reduces degradation of apolipoprotein B, and leads to hypertriglyceridemia due to increased production of VLDL." (PMID 17597538, 2007). "Additionally, in severe hypertriglyceridemia (TG >10.0 mmol/L; 885 mg/dl) ApoB immunoassays are compromised by analytical interference in blood samples due to turbidity caused by large chylomicron and VLDL particles." (PMID 39171323, 2024). "However, since the blood-based discriminators (such as hypertriglyceridemia, APOB, TRIG, LDLC, and HbA1c) are common denominators for metabolic diseases, these are poor biomarkers for carotid atherosclerosis on their own." (PMID 34692558, 2021). "Lastly, although LDL-C remains an important treatment target, other broader measures of atherogenic lipoprotein burden, such as non–HDL-C and apolipoprotein B, may be considered in hypertriglyceridemia according to recent guidelines." (PMID 34709388, 2021). "Moreover, vildagliptin regulates lipid metabolism; attenuates postprandial hypertriglyceridemia; and lowers serum triglycerides, apolipoprotein B, and blood total cholesterol levels." (PMID 32218354, 2020).
hypertriglyceridemia (continued). "Hypertriglyceridemia, higher levels of low-density lipoprotein cholesterol, lipoprotein(a) particles, and apolipoprotein B (Apo B)-containing lipoproteins, as well as low high-density lipoprotein (HDL) levels, are the most frequent alterations observed in CKD patients." (PMID 33255769, 2020). "Here, we describe, that transgenic mice overexpressing the human APOB-100 protein show chronic hypertriglyceridemia, an increase in permeability for a small molecular marker, and gene expressional, immunohistochemical and ultrastructural alterations at the BBB." (PMID 30410436, 2018). "Additionally, patients with hypertriglyceridemia had slightly younger age and higher BMI, as well as the higher levels of TC and apoB, and the lower levels of HDL cholesterol." (PMID 25803284, 2015). "These risk factors include, but are not limited to, obesity, metabolic syndrome, hypertriglyceridemia, apolipoprotein B, lipoprotein (a), homocysteine, pro-thrombotic factors, pro-inflammatory factors as well as measures of subclinical atherosclerotic cardiovascular disease (ASCVD)." (PMID 25154373, 2014). "Lipoprotein profile, an independent risk factor of cardiovascular disease, is abnormal in CKD patients including lower HDL cholesterol, increasing the rate of apolipoprotein A1 catabolism, hypertriglyceridemia, high level of apolipoprotein B and total cholesterol but normal apo A level." (PMID 20535268, 2010). "This would lead to an increase in the secretion of VLDL-TAG and apolipoprotein B100 (apoB100) from the liver, and hence may account for the observed hypertriglyceridaemia in group B compared to group A." (PMID 20670429, 2010). "Thus, the available guidelines advise the use of non-HDL-C (or ApoB) as a secondary treatment target in high-risk or very high risk patients with mild-to-moderate hypertriglyceridemia." (PMID 36613514, 2022). "This cascade exemplifies the atherogenic triad of lipid abnormalities: hypertriglyceridemia, low HDL-C, and small, cholesterol-depleted LDL particles with a high apoB content relative to cholesterol." (PMID 41483441, 2026). "Lipid abnormalities among CKD patients encompass hypertriglyceridemia, elevated LDL-C, ApoB accumulation, diminished HDL-C, lowered ApoA, and elevated lipoprotein (a) concentration." (PMID 38419057, 2024). "As plasma TG increases, this proportion can reach 15–20%, but even in severe hypertriglyceridemia (except for dysbetalipoproteinemia), LDL particles make up the great majority of apoB particles." (PMID 39334349, 2024). "This explains the classic type B phenotype commonly seen in hypertriglyceridemia, in which LDL-C is normal or only slightly elevated, whereas apoB is almost always elevated." (PMID 37685804, 2023). "The green cluster includes triglycerides (TG), hypertriglyceridemia, LDL-C, apolipoprotein b (ApoB), lipoprotein, omega-3 fatty acids, icosapent ethyl, PCSK9 inhibitors, eicosapentaenoic acid (EPA), docosahexaenoic acid (DHA)." (PMID 38017531, 2023). "Apolipoprotein-B and LDL levels were within goal ranges, at 116 g/L and 103 mg/dL, respectively, indicating this was primary hypertriglyceridemia." (PMID 33308287, 2020). "Hypertriglyceridemia, higher levels of LDL cholesterol, lipoprotein(a) particles, and apolipoprotein B (Apo B)-containing lipoproteins as well as low high-density lipoprotein (HDL) levels are most frequent alterations observed in CKD patients." (PMID 31963445, 2020). "At concentrations of 0.25% and 0.5% AI, dose-dependent improvements were observed in the major parameters of hypertriglyceridemia, such as plasma TG, FFA, ApoB, and LPL levels." (PMID 28805698, 2017). "There were also positive correlations between AUC-TG and apoB-48 at 0, 2, 6, and 8 hours, AUC-apoB-48, apoB at 2, 4, 6, and 8 hours, and AUC-apoB suggesting that both chylomicrons and VLDL contribute to postprandial hypertriglyceridaemia." (PMID 26989412, 2016).
hypertriglyceridemia (continued). "Early studies in APOC3 transgenic mice concluded that the hypertriglyceridemia in those mice is not due to increased hepatic TRL APOB production or decreased lipolysis by LPL but rather results primarily from decreased tissue uptake of TRLs from circulation." (PMID 37972731, 2024). "This is likely because apoB, which provides a metric of the total particle number of atherogenic lipoproteins, does not decrease with hypertriglyceridemia unlike LDL-C." (PMID 39526185, 2024). "ABCA1-dependent efflux was also increased using apoB-depleted serum from T2DM patients with hypertriglyceridemia compared to T2DM patients without hypertriglyceridemia." (PMID 36837872, 2023). "Additionally, apoB measurement is cost-effective, does not require fasting, and remains reliable even in the presence of hypertriglyceridemia or reduced LDL-C levels due to lipid lowering therapy." (PMID 40852379, 2025). "This protective effect is consistent with APOC3 inhibition via volanesorsen reducing hepatic steatosis in patients with hypertriglyceridemia, and substantial evidence suggests APOC3 deficiency, unlike APOB deficiency, is cardioprotective without causing steatosis." (PMID 40065360, 2025). "Secondary treatment targets, such as non-HDL cholesterol and apolipoprotein B, may be used to treat mild or moderate hypertriglyceridemia." (PMID 40452043, 2025). "It is now accepted that using ApoB to assess ASCVD risk in hypertriglyceridaemia (2–10 mmol/L) better reflects the total number of atherogenic particles than do LDL-C or non-HDL-C, particularly in patients with hypertriglyceridemia." (PMID 39171323, 2024). "The causality of hypertriglyceridemia in cardiovascular diseases is not yet established; however, there is evidence that lowered triglyceride levels caused by the LDL receptor gene lower the risk of CHDs via the reduction of apoB lipoproteins." (PMID 38892018, 2024). "The most recent European Society of Cardiology and European Atherosclerosis Society (ESC/EAS) guidelines also provide both secondary non-HDL-C and apoB targets, and state that apoB may be the preferred test in patients with hypertriglyceridemia." (PMID 37685804, 2023). "According to the apoB algorithm, type IIa (HLP2a) and IIb (HLP2b) are identified by apoB ≥ 120 mg/dL together with variable plasma TG levels, while type I (HLP1), III (HLP3), IV (HLP4), and V (HLP5) are identified by apoB < 120 mg/dL with moderately to severe hypertriglyceridemia (HTG)." (PMID 36675730, 2022). "However, LZP deficiency attenuates apoB-mediated VLDL secretion, leading to lower serum apoB and TG levels in mice; therefore, LZP could be considered a potential therapeutic target for hyperlipemia, especially hypertriglyceridemia." (PMID 33591966, 2021). "Heterogeneity in apoB metabolism in hypertriglyceridemia is not confined to the VLDL density range." (PMID 32477261, 2020). "However, this estimation is not applicable to patients with hypertriglyceridemia because TG-rich lipoprotein apoB is contaminated with plasma apoB." (PMID 28125987, 2017). "In contrast, studies of statin monotherapy show significantly larger magnitude reductions in LDL-C and non-HDL-C versus apoB in a wide variety of patient populations, including those with T2DM and hypertriglyceridemia." (PMID 27405296, 2016). "As a result, apoB concentration will always be a slight overestimation of the number of LDL particles, although the number of VLDL particles in most patients with hypertriglyceridemia will not exceed 10% of the total number of LDL particles." (PMID 34955672, 2022).
myocardial infarction (141 papers, 2007 to 2026). Gross necrosis of the myocardium, as a result of interruption of the blood supply to the area, as in coronary thrombosis. "ApoB is an independent risk factor for major adverse cardiovascular events (MACE) following myocardial infarction." (PMID 41030852, 2025). "Based on a large international case–control study (INTERHEART) spanning 52 countries, the ApoB:ApoA1 ratio was shown to be a better marker for heart attack risk than the traditional TC:HDL-C ratio." (PMID 40944180, 2025). "ApoB is an independent risk factor for residual risk after myocardial infarction and, when combined with traditional risk indicators, can better predict cardiovascular residual risk." (PMID 41030852, 2025). "Data from the AMORIS study demonstrated that ApoB and the ApoB/ApoA1 ratio improve risk prediction for fatal myocardial infarction beyond LDL-C in large populations." (PMID 41226966, 2025). "By binary logistic regression analysis, higher levels of ApoB were significantly associated with the occurrence of adverse cardiovascular events after myocardial infarction after adjustment for multifactorial variables." (PMID 41030852, 2025). "Elevated ApoB levels are more advantageous than elevated LDL-C levels in assessing the severity of coronary artery stenosis in myocardial infarction patients and predicting residual risk after myocardial infarction." (PMID 41030852, 2025). "Plasma concentration of apoB and the apoB/apoA1 ratio have been reported to strongly relate to increased risk of fatal myocardial infarction in both men and women." (PMID 40129271, 2025). "Our study provides insight into the value of ApoB in assessing the degree of coronary artery stenosis in patients with myocardial infarction and in predicting residual risk after myocardial infarction." (PMID 41030852, 2025). "The relationship between ApoB and the severity of acute myocardial infarction as well as residual risk still needs to be further determined." (PMID 41030852, 2025). "Serum levels of ApoA1 in healthy patients are ∼1.5 g/L in healthy volunteers and slightly lower in those at risk for myocardial infarction, ∼1.25 g/L, and in the same groups, the ApoB levels were 1.08 g/L and 1.18 g/L, respectively." (PMID 38479648, 2024). "A similar tendency was observed in another cohort, where ApoB was the only biomarker significantly associated with incident myocardial infarction in fully adjusted models." (PMID 38674207, 2024). "In a prospective study, which included over 430,000 patients, split into two groups (the primary and the secondary prevention group), apoB was the only independent predictor of the risk of myocardial infarction." (PMID 37629496, 2023). "Other studies reported that ApoB/ApoA ratio is correlated with the risk of myocardial infarction and carotid intima-media thickness in patients with T2DM." (PMID 36673620, 2023). "The apoB to apoA1 ratio has been suggested as superior to traditional risk markers in a case–control study of acute myocardial infarction comprising >20.000 participants." (PMID 36501072, 2022). "The AMORIS study found a strong direct relationship between ApoB and risk of myocardial infarction (MI) and an indirect inverse relationship between ApoA1 and risk of MI." (PMID 35295919, 2022). "Both ApoB/ApoA1 ratios were considered a better risk predictor to acute myocardial infarction than the TC/HDLc ratio." (PMID 33725226, 2021). "We and others have shown that both apoB and apoA-1, and the balance of these apolipoproteins, expressed as the apoB/apoA-1 ratio, are strongly associated with myocardial infarction (MI) and stroke." (PMID 34851955, 2021). "The apolipoprotein B/apolipoprotein A-I ratio was shown to be strongly related to the risk of myocardial infarction in several large-scale studies." (PMID 32449038, 2020). "In several large-scale studies, the apoB/apoA-I ratio was related strongly to the risk of development of myocardial infarction and other cardiovascular diseases." (PMID 32449038, 2020).